APOE (apolipoprotein E)
Diseases named in the same sentence as APOE in open-access papers (continued):
Sharing a sentence is not in itself a finding about the gene and the disease.
Hypercholesterolemia (continued). "The ApoE KO mouse model spontaneously develops hypercholesterolemia and atherosclerotic vascular lesions." (PMID 31575906, 2019). "Editor's choice:ApoE knockout pigs displayed severe hypercholesterolemia and spontaneously developed human-like atherosclerotic lesions in the aorta and coronary arteries within 6 months of feeding on a high-fat and high-cholesterol diet." (PMID 30305304, 2018). "The present study shows, for the first time, that hypercholesterolemia and aging leads to monocytosis, oxidative stress and, consequently, genomic instability and apoptosis in monocytes of aged apoE−/− mice." (PMID 30185234, 2018). "We have found that ApoE KO pigs fed an HFHC diet had severe hypercholesterolemia and spontaneously developed human-like atherosclerotic lesions in the aorta and coronary arteries." (PMID 30305304, 2018). "In conclusion, ApoE−/− pigs fed a HFHC diet showed severe hypercholesterolemia and developed progressive atherosclerotic lesions." (PMID 30305304, 2018). "In ApoE−/− mice, hypercholesterolemia accelerates lipid deposition, atherosclerosis, and chronic inflammation." (PMID 30049280, 2018). "ApoE-/- mice develop hypercholesterolemia and complex atherosclerotic plaques that closely mimic human lesions." (PMID 29593532, 2018). "Depletion of the ApoE protein leads to spontaneous hypercholesterolemia and atherogenesis manifested in mature atherosclerotic plaques." (PMID 29208753, 2018). "High expression of APOE during the early stages of hypercholesterolemia also has an impact on the cholesterol homeostasis in the brain." (PMID 28432486, 2017). "Hypercholesterolemia is known to induce selective expansion of Gr1+/Ly6Chigh monocytes in ApoE–/– mice, and these cells preferentially adhere to activated endothelium, infiltrate the arterial wall and develop into atherosclerotic macrophages." (PMID 28069704, 2017). "ApoE−/− mice also developed severe hypercholesterolemia, showing an almost 3.8-fold increase in total cholesterol (TC) compared with WT controls of the same age." (PMID 28475147, 2017). "High expression of APOE during the early stages of hypercholesterolemia also has an impact on the homeostasis of cholesterol in the brain." (PMID 28432486, 2017). "The widely accepted model devoid of such drawback is apoE-knockout (apoE-/-) mice, which spontaneously develop hypercholesterolemia, dyslipidemia, and arterial lesions on the chow diet." (PMID 28777310, 2017). "ApoE knockout mice exhibited significant hypercholesterolemia (400 mg/dl, which represents a five-fold increase in plasma cholesterol level compared to wild type mice) despite being on a low fat diet." (PMID 28095860, 2017).
Hypercholesterolemia (continued). "In this study, we demonstrated that intake of 0.2% and 2% of cocoa powder improved hypercholesterolemia and inhibited aortic atherosclerosis in apoE KO mice." (PMID 26980943, 2016). "ApoE-KO mice develop severe hypercholesterolemia and atherosclerotic lesions mimicking atherogenesis in humans." (PMID 27019366, 2016). "In contrast, hypercholesterolemia induced either extrinsically (atherogenic/high fat diet) or intrinsically by deletion of apolipoprotein E gene (apoE−/− mice), is crucial for increased host protection against visceral L. donovani infection in mice." (PMID 27632901, 2016). "It is possible that the APOE genotype exerts differential effects on men and women through its influence on earlier disease processes (e.g., hypercholesterolemia) that have later downstream effects." (PMID 27486898, 2016). "In conclusion, dietary cocoa powder improves hypercholesterolemia and inhibits aortic atherosclerosis in apoE KO mice." (PMID 26980943, 2016). "In the current study we aim to genetically dissect the tissue-specific roles of apolipoprotein E for diet-induced obesity and hypercholesterolemia using a novel conditional transgenic mouse model." (PMID 26695075, 2015). "Both apoE-/- and apoE-/-VDR-/- mice developed marked hypercholesterolemia, with a similar lipid profile within each gender." (PMID 26322890, 2015). "In the current study we established a novel mouse model for conditional apoE deficiency to investigate the role of adipocyte and hepatocyte apoE for hypercholesterolemia and diet-induced obesity." (PMID 26695075, 2015). "Our data demonstrates that the removal of the ovaries from ApoE mice lead to remarkable renal dysfunction, indicating that endogenous female sex hormones can play a protective role against hypercholesterolemia-induced kidney injury." (PMID 25422135, 2014). "Ovariectomy did not modify this parameter in C57 animals; however, it exacerbated hypercholesterolemia in the ApoE OVX group." (PMID 25422135, 2014). "The combination of atherosusceptible gene changes and hypercholesterolemia leads to the significant Ca2+ signalling changes that we see in ApoE−/− aortic arch." (PMID 25344475, 2014). "Ovariectomy did not modify plasma cholesterol levels in the C57 OVX group (64 ± 2 mg/dL), however it intensified hypercholesterolemia in the ApoE OVX group (645 ± 38 mg/dL, p < 0.01)." (PMID 25422135, 2014). "Together the results indicate that Western diet-induced hypercholesterolemia specifically expands aortic and splenic γδT17 cells in ApoE KO mice." (PMID 25313857, 2014). "As one approach to this problem, the adenovirus-mediated restoration of apolipoprotein E (ApoE) expression in ApoE−/− mice was shown to reverse hypercholesterolemia and reduce foamy macrophage burden in lesions." (PMID 24741577, 2014). "As expected, ApoE mice present hypercholesterolemia (Sham: 345 ± 14 mg/dL, p < 0.01) when compared to C57 animals (Sham: 52 ± 4 mg/dL)." (PMID 25422135, 2014). "In 10 week old ApoE−/− mice, we observed that hypercholesterolemia differentially affects Ca2+ signalling in endothelial cells from aortic arch and thoracic aorta." (PMID 25344475, 2014). "The hypercholesterolemia in apoE−/− mice results mainly from the increased levels of E−/B48 lipoproteins." (PMID 23984090, 2013). "Our group previously showed an increase in oxidative processes related to the retinal morphological alterations observed in apoE−/− mice and other models of hypercholesterolemia." (PMID 23738034, 2013). "As expected, similar cold-induced hypercholesterolemia, plaque growth, and instability were also seen in these regular chow-fed ApoE−/− mice." (PMID 23823482, 2013). "It is noteworthy to mention that human apoE is less effective than murine apoE in mediating lipoprotein clearance in mice particularly in response to diet-induced hypercholesterolemia due to its lower affinity for murine LDL receptors." (PMID 22606237, 2012).
Hypercholesterolemia (continued). "Familial Hypercholesterolemia results from mutations in the LDL receptor, ApoB, PCSK9, and ApoE genes." (PMID 22111029, 2012). "WT mice were used to assure that potential antigenic exposure from serum cholesterol as confounding factors would be kept at a minimum given the severe levels of hypercholesterolemia in apoE-/- mice." (PMID 22347402, 2012). "Twenty years ago plasma-purified or recombinant ApoE protein were infused into rabbits with genetic or diet-induced hypercholesterolaemia." (PMID 22645694, 2012). "We next wondered whether LysM-Cre–mediated gene repair of the Apoeh/h allele would increase apoE expression levels in Kupffer cells, and whether this additional source of apoE could have contributed to raise plasma apoE levels and reduce diet-induced hypercholesterolemia in Apoeh/hLysM-Cre mice." (PMID 22606237, 2012). "One important feature we found was that fructose-rich diet promotes a proatherogenic state in ApoE-KO mice, independently of hypercholesterolemia, leading to accelerate aortic and carotid atheroma development." (PMID 22474431, 2012). "APOE expression in PBMC is modulated by hypercholesterolemia and the APOE mRNA level regulates the plasma lipid profile." (PMID 22074026, 2011). "The purpose of this study is to investigate the effects on APOE mRNA expression profile of hypercholesterolemia and APOE genotypes using PBMC from normolipidemics and hypercholesterolemic individuals." (PMID 22074026, 2011). "ApoE-KO mice are known as an animal model of hypercholesterolemia, in which the plasma concentrations of Chol are approximately 14-fold higher than in WT mice, even when maintained on normal chow (7.20±0.16 vs. 0.50±0.01 mg/mL)." (PMID 21857965, 2011). "We evaluated the effects on APOE expression of hypercholesterolemia, APOE ε2/ε3/ε4 genotypes and atorvastatin treatment in Brazilian individuals." (PMID 22074026, 2011). "Studies have shown that young (6-19-week-old) male apoE-/- mice fed a standard chow diet (hypercholesterolemia only) have a preserved endothelial NO-dependent relaxation response to ACh in cutaneous vessels and in the mesenteric vascular bed." (PMID 22082357, 2011). "These genetic disorders include LPL -/-, apoE 2/2, apoE 4/4, homozygous familial hypercholesterolemia, homozygous familial defective apoB, and S447X - a single nucleotide polymorphism in the LPL gene." (PMID 22029862, 2011). "This murine model that lack the gene encoding apoE and LDL receptor knockout develop spontaneous hypercholesterolemia/hyperlipoproteinemia." (PMID 20727187, 2010). "Thus, knockout of ApoE in mice results in hypercholesterolemia, monocyte proliferation and infiltration into the intima 15-18, oxidative stress, and spontaneous development of atherosclerotic lesions." (PMID 41583528, 2026). "The study of vulnerable plaque models in hypercholesterolemia ApoE (−/−) mice and NR1D1 (−/−) ApoE (−/−) mice revealed that NR1D1 deficiency could significantly increase the vulnerability/rupture of plaques." (PMID 40255337, 2025). "Interestingly, male apoE KO rabbits exhibited significantly “higher” hypercholesterolemia than WT rabbits, while female apoE KO rabbits showed almost “similar” hypercholesterolemia starting from 8 weeks (n.s.)to WT counterparts." (PMID 39087075, 2024). "With absence of an APOE ε2 allele or a greater number of ε4 alleles, people had a greater prevalence of hypercholesterolemia and family history of AD." (PMID 38472178, 2024). "Collectively, this suggests that hypercholesterolemia induced by WD leads to hepatic ER stress markers in WD-fed ApoE−/− mice and that these changes could be mitigated by DADS supplementation." (PMID 37138269, 2023). "In addition, the effect of hypercholesterolemia on mammary tumor growth and metastasis was also studied in APOE knockout mice." (PMID 37312170, 2023).
Hypercholesterolemia (continued). "The first step was to confirm that ApoE−/− mice gained body weight, showed increased visceral and subcutaneous adiposity in addition to hypertriglyceridemia and hypercholesterolemia in comparison with Control STD, being significantly higher in ApoE−/− mice fed with HFD for 18 weeks." (PMID 37605307, 2023). "The ApoE knockout model was the first genetically modified atherogenic murine model developed in which ApoE knockout mice exhibited significant hypercholesterolemia, having a five-fold increase in plasma cholesterol level relative to wild-type mice despite being on a low-fat diet." (PMID 37507899, 2023). "This was accompanied by a drop in hepatic TG content and liver weight, indicating that hypercholesterolemia induced hepatic ER stress in the WD-fed ApoE -/- mice and that these changes could be reversed by capsaicin supplementation." (PMID 38084147, 2023). "We used ApoE−/− mice for our studies, because this is an established mouse model that develops spontaneous severe hypercholesterolemia, elevated vascular ROS and cytokine levels, endothelial dysfunction, and atherosclerotic lesions similar to those seen in humans in various arteries." (PMID 37873768, 2023). "In previous research, some authors have shown that ESGA attenuates hypercholesterolemia and hepatic cholesterol lipid synthesis by suppressing acyl-coenzymeA (CoA): cholesterol acyl-transferase (ACAT) in apoE-deficient mice and by attenuating IR in HFD-fed rats." (PMID 38004149, 2023). "It suggested that even during hypercholesterolemia caused by ApoE-/- absence, no NETs were formed because NE and PR3 were neutralized by the DNase, proving that these two are paramount for NET formation." (PMID 36851139, 2023). "Our analysis identified four colocalized genes, CELSR2, PCSK9, LPA, and APOE, that are involved in lipid metabolism and may contribute to the development of both Pure hypercholesterolaemia and IHD." (PMID 38144368, 2023). "In this study, supplementation with DADS improved leptin resistance and decreased plasma cholesterol, suggesting that DADS intake may improve hyperleptinemia and hypercholesterolemia in WD-fed ApoE−/− mice." (PMID 37138269, 2023). "In this study, we have determined whether TIMEx consumption protects against dyslipidemia, including hypertriglyceridemia and hypercholesterolemia, in ApoE−/− mice." (PMID 35208189, 2022). "Hypercholesterolemia increases ROS production and endothelial dysfunction in ApoE‐KO mice." (PMID 35307922, 2022). "In ApoE KO mice, SR-B1 deletion (SR-B1/ApoE dKO) produces severe hypercholesterolemia (≈1000 mg/dl) with a significant increase in lipoprotein-FC and HDL particles in the size range of LDL and VLDL, with defects in morphology and function like those seen in human congenital heart disease." (PMID 35332444, 2022). "Most compelling is the fact that ApoE-/- combined with SCI worsens hypercholesterolemia, in particular, which may be one antecedent to the increased AD burden we observe." (PMID 33626069, 2021). "Previous studies have also marked the APOE ε4 allele as a determinant for hypercholesterolemia in the Algerian population and other non-Hispanic populations." (PMID 34828374, 2021).
Hypercholesterolemia (continued). "Collectively, these data suggest that the severe pathology observed in Dscr-1 and ApoE double null mutant mice is based on advanced hypercholesterolemia rather than the indirect effects of ApoE loss." (PMID 33895138, 2021). "A case-control study showed that participants residing in Valencia, Spain, that were APOE ε4 allele carriers had a higher risk of hypercholesterolemia than those that were not APOE ε4 allele carriers." (PMID 34828374, 2021). "Specifically, possible genetic interactions, such as with the apolipoprotein E E4 (ApoEε4) genotype, which has been associated with cognition, especially in the presence of hypercholesterolemia, was not able to be accounted for in the current analyses." (PMID 34966270, 2021). "Increasing studies suggest an association between APOE ε4 allele and hypercholesterolemia in non-Hispanic populations." (PMID 34828374, 2021). "In this context, the purpose of the present study was to investigate and compare the effects of six weeks of HIIT and MICT on the hypercholesterolemia model of ApoE KO mice fed HFD, with a special focus on the changes in redox homeostasis and myokine production in the skeletal muscle." (PMID 34206159, 2021). "Hypercholesterolemia was induced in ApoE−/− mice fed on cholesterol‐enriched diet for 12 weeks." (PMID 32566176, 2020). "However, in the previous study the rats were younger (6–9 weeks old) and fed a standard diet while in the current study, ApoE KO rats were fed a Western diet and developed significant hypercholesterolemia." (PMID 32943715, 2020). "In the present study, we show that HF feeding (60% kcal from fat and 0.15% cholesterol) induces obesity, hypercholesterolemia, inflammatory disorders and endothelial dysfunction in young (10-wk-old at the beginning of the treatment) ApoE−/− mice fed a HF diet for only 8 weeks." (PMID 31578395, 2019). "The aim of the present study was to investigate the long-term effects of hypercholesterolemia on MI-R induced injury in APOE*3-Leiden mice, concomitantly studying the effectivity and reproducibility of a small animal model more closely mimicking the clinical situation." (PMID 31199833, 2019). "In a mouse model combining hyperglycaemia and hypercholesterolaemia (streptozotocin diabetic, ApoE‐/‐ mice), mice showed severe insulin resistance, renal dysfunction, micro‐inflammation, subsequent extracellular matrix expansion and decreased expression of PTPN2." (PMID 30955247, 2019). "Hypercholesterolemia in apoE−/− mice stimulated a significant increase in LEC numbers over WT LN." (PMID 30972070, 2019). "Hypercholesterolemia triggers oxidative stress due to increased production of O2– and degradation and/or inactivation of NO, leading to endothelium-dependent relaxation dysfunction in ApoE KO animals." (PMID 31695628, 2019). "Only the presence of hypercholesterolaemia displayed variation between APOE genotypes." (PMID 29317609, 2018). "In addition, APOE-deficient mice are characterized by severely disrupted LDL-receptor mediated lipoprotein remnant clearance and severe hypercholesterolemia." (PMID 29401645, 2018). "ApoE−/− mice are considered a well-accepted model of hypercholesterolemia." (PMID 30049280, 2018).